BCL2 (BCL2 apoptosis regulator)
Diseases named in the same sentence as BCL2 in open-access papers (continued):
Sharing a sentence is not in itself a finding about the gene and the disease.
Cognitive impairment (47 papers, 2017 to 2026). Abnormal cognition is characterized by deficits in thinking, reasoning, or remembering. "Based on our current data in combination with existing literatures, it is plausible that TET1 protein deficiency and demethylation disorders of the Bcl2 promotor likely contribute to a potential mechanism underlying fluoride elicited cognitive disorders." (PMID 40133886, 2025). "Additional research has verified that ginsenoside Rg2 reduces cognitive impairment caused by Aβ25-35, raises the Bcl-2/Bax ratio, and prevents the rat model of caspase-3 cleavage by initiating the PI3K/Akt pathway." (PMID 39399315, 2024). "The present findings supported earlier studies that cadmium-evoked cognitive deficit was linked to elevated hippocampal Bax, decreased Bcl-2, and activated GSK-3β." (PMID 37765022, 2023). "In accordance with previous data, the current study depicted that cadmium-induced cognitive impairment in rats was associated with exaggerated neuronal apoptosis as seen by upregulated expression of hippocampal Bax together with downregulation of the anti-apoptotic Bcl-2." (PMID 37630980, 2023). "In the present study, inosine treatment decreased Bax, Caspase-9, and Caspase-3 mRNA levels and upregulated Bcl-2 expression in HT-22 cells, thereby alleviating D-gal-induced cognitive impairment in mice." (PMID 41596947, 2026). "Our results indicate that TET1 mitigates prenatal fluoride-induced cognitive impairment, at least in part, by modulating Bcl2 DNA hydroxymethylation and the consequently reducing neuron apoptosis." (PMID 40133886, 2025). "Many studies reported that Aβ over-deposition in the brain would cause neuronal apoptosis by modulating the expression of the Bax/Bcl-2 ratio and result in cognitive impairment and neurodegenerative disease." (PMID 37511827, 2023). "Together, these data indicate that H2 inhalation ameliorated the TMT-induced toxicity and cognitive impairment in mice by inhibiting hippocampal apoptosis through Bcl-2 and Bax signaling pathways." (PMID 34948107, 2021). "Furthermore, Gu and other researchers found that the Aβl-42 peptide caused neurodegenerative changes in a stereotaxic rat model of AD, including cognitive impairment, increased pro-apoptotic markers (Bax, caspase-3 and -9), and decreased Bcl-2 and BDNF levels." (PMID 40430064, 2025). "Acupuncture ameliorated cognitive impairment in VD rats, reduced hippocampal neuronal damage and apoptosis, downregulated pro-apoptotic proteins (cleaved-caspase 3 and Bax), and upregulated anti-apoptotic Bcl-2." (PMID 41291751, 2025). "Furthermore, neuronal apoptosis and increased Bax/Bcl2 in the hippocampus are consistent with cognitive impairment." (PMID 36143409, 2022). "However, IMP-treatment obviously reversed the level of Bax, Bcl-2, Caspase-3 and improved cognitive impairment in 2VO rats." (PMID 33883654, 2021). "In addition, luteolin in hippocampal tissue of rats also prevents from cognitive impairment, learning and memory impairment, reductions in choline acetyl transferase activity, antioxidant enzymes concentrations, Bcl‐2/Bax ratio, and also enhancement in MDA level." (PMID 39830909, 2025). "For example, in patients at early symptomatic stages, when cognitive impairment is first detected, enhancing physiological apoptotic pathways using Bcl-2 or Bcl-xL inhibitors, or promoting the cell competition pathway described here, may have strikingly beneficial effects." (PMID 30590040, 2018). "Babaei and coworkers employed a similar method for AD induction using the Aβl-42 peptide, which resulted in cognitive impairment, a decline in BDNF, NGF, and Bcl-2 levels, and an increase in Bax and caspase-3 expression." (PMID 40430064, 2025). "Reduce HIF-1α and Bax expression, increase Bcl-2 expression, initiate the PI3K/Akt pathway, and improve cognitive impairment." (PMID 39399315, 2024).
Cognitive impairment (continued). "It improved cognitive impairment and neuronal injury in rats by reducing the expression of TNF-α, IL-1β, COX-2, decreasing the Bax/Bcl-2 ratio, levels of Aβ1-42 and active-caspase-3, as well as IκB-αdegradation and p-NF-κB p65 activation." (PMID 39081953, 2024). "Taken together, the results of this study have demonstrated that tilianin attenuates cognitive impairment in VaD by regulating miR-193b-3p/CaM and miR-152-3p/CaMKIIα mediated p38 MAPK/NF-κB inflammatory and Bcl-2/Bax/caspase-3/PARP apoptotic pathways." (PMID 37153565, 2023). "Spinosin has been reported to alleviate cognitive impairment by improving the neurotrophic factor (BDNF) and Bcl-2, decreasing the level of MDA, and inhibiting the inflammatory factor IL-6 in the brain." (PMID 36193419, 2022). "An experimental study reported that in Aβ42-induced rats, β-asarone ameliorated cognitive impairment and reversed the increase of apoptosis in the hippocampus by inhibiting JNK activation, upregulating Bcl-w and Bcl-2, and inhibiting caspase-3 activity." (PMID 35215287, 2022). "Additionally, the included studies have demonstrated that acupuncture reduces NO and Bax expression, increases Bcl-2, MDA, GSH-Px, ADMA, Ras, and ERK1/2 expression, and improves cognitive function in sleep disorder-induced cognitive impairment models." (PMID 40177248, 2025). "In conclusion, Yisui multipurpose soup could effectively protect D-galactose-induced neuronal cell cognitive impairment by orchestrating expressions of the inflammatory factors TNF-α, iNOS, NO, and IL-1β and the apoptosis-related proteins Bcl-2 and Bax." (PMID 35754679, 2022). "This combination of Chinese and Western drug therapy decreased the seizure severity and SRS frequency, markedly improved cognitive impairment and significantly decreased neuronal damage by up-regulating the expression of GDNF proteins and the level of Bcl-2/Bax in the hippocampal CA3 region." (PMID 29560767, 2018). "This study suggests that LA treatment could improve cognitive impairment in MCAO rats to enhance the cholinergic system in the hippocampal CA1 region and to exert a neuroprotective effect by regulating Creb, Bdnf, Bcl-2, and Bax gene expressions." (PMID 28408940, 2017). "It suggests that LA treatment could improve cognitive impairment in MCAO rats to enhance the cholinergic system in the hippocampal CA1 region and to exert a neuroprotective effect by regulating Creb, Bdnf, Bcl-2, and Bax gene expressions." (PMID 28408940, 2017). "However, Bcl-2 overexpression neither inhibited hippocampal cell death nor inhibited the motor and cognitive deficits." (PMID 37417988, 2024).
nasopharyngeal carcinoma (46 papers, 2009 to 2025). A carcinoma arising from the nasopharyngeal epithelium. "Nasopharyngeal carcinoma shows up to five mutations including DN-P63, P27, cyclin D1 and BCL-2 associated with its development and manifestation which is consistent with our convexity-upwards log-log model." (PMID 40720480, 2025). "Down-regulation of GnT-V enhances nasopharyngeal carcinoma cell radiosensitivity both in vitro and in vivo, and is linked to the G2-M cell cycle arrest and the reduction of the BcL-2/Bax ratio." (PMID 24349959, 2013). "All these indicate that miR-19b-3p, miR-125b, miR-21, and miR-205, which are elevated in nasopharyngeal carcinoma, promote radiotherapy resistance through the bcl-2 apoptosis family, while miR-185 causes nasopharyngeal cancer cells sensitive to radiation therapy." (PMID 32328201, 2020). "Decreased expression of Bcl-2 following downregulation of Mgat5 has also been observed in nasopharyngeal carcinoma." (PMID 38912584, 2024). "The overexpression of Tgfβr3 in nasopharyngeal carcinoma cells has been demonstrated to increase apoptosis through the downregulation of Bcl2." (PMID 35625614, 2022). "This suggests that inhibiting the expression of EBV-miR-BART5-3p can promote the apoptosis of nasopharyngeal carcinoma cells by downregulating Bcl-2 protein and upregulating Bax and Caspase-3 protein expressions." (PMID 36225172, 2022). "BCL2, as a target gene for growth and development of nasopharyngeal carcinoma cells, is a poor prognostic marker for nasopharyngeal carcinoma." (PMID 32595725, 2020). "Ectopic expression of miR-125b-5p using mimics significantly increased cisplatin induced cytotoxicity, apoptosis and chmosensitivity by down-regulating Bcl2 both in nasopharyngeal cancer and gallbladder cancer." (PMID 28968424, 2017). "Tumor suppressor PDCD4 modulates miR-184-mediated direct suppression of C-MYC and BCL2 blocking cell growth and survival in nasopharyngeal carcinoma." (PMID 32309578, 2016). "TET induces apoptosis in nasopharyngeal carcinoma CNE cells by down-regulating Bcl-2 mRNA and up-regulating Bax mRNA expression." (PMID 27754332, 2016). "We previously have reported that ApoG2 is a promising compound that kills nasopharyngeal carcinoma (NPC) cells by inhibiting the antiapoptotic function of Bcl-2 proteins." (PMID 19698176, 2009). "Some studies also reported the overexpression of BCL2 in nasopharyngeal carcinoma, which may play an important role in lymph node metastasis." (PMID 39409902, 2024). "Therefore, in our present study, efforts were made to explore the correlation and effect of BAX -248 G>A and BCL2 -938 C>A SNPs on nasopharyngeal carcinoma (NPC) patients’ survival." (PMID 33906310, 2021). "Although the function of NEAT1/miR-129 and miR-129/Bcl-2 axis was studied in multiple cancers, it remains unclear their correlation and function in the nasopharyngeal cancer (NPC), especially in term of the HDACi response." (PMID 32692721, 2020). "Later, in nasopharyngeal carcinoma, miR-184 could block cell growth and survival by directly targeting BCL2 and C-MYC19." (PMID 30833572, 2019). "Bcl-2 targeted by miR-184 promotes cell apoptosis in nasopharyngeal cancer." (PMID 27083050, 2016). "MiR-184 suppresses cell growth and survival in nasopharyngeal cancer via targeting Bcl-2." (PMID 27083050, 2016). "Besides, miR-129 specifically downregulates BCL2 protein levels in nasopharyngeal cancer cells." (PMID 40730640, 2025). "On the other hand, capsaicin also induces G1 arrest and apoptosis of nasopharyngeal cancer cells through mitochondrial depolarization and acting on specific pathways (PI3K/mTOR) and molecules (caspase-3, Bcl-2)." (PMID 33609025, 2021). "Zhen and coworkers reported that miR-184 targeted and inhibited BCL2 and CMYC transcripts in nasopharyngeal carcinoma." (PMID 27730344, 2017).
nasopharyngeal carcinoma (continued). "Furthermore, in nasopharyngeal carcinoma, the combination of gemcitabine with APG‐1252, a novel inhibitor of Bcl‐2/Bcl‐xl, exhibited additive antitumor effects." (PMID 40405831, 2025). "Over-expression of BCL-2 and related family proteins (BCL-xL and MCL-1) confers anti-apoptotic response and contributes to the development of resistance to chemotherapy and radiation treatment for nasopharyngeal carcinoma (NPC)." (PMID 34064109, 2021). "In nasopharyngeal carcinoma, in vitro studies pointed out that the mechanism by which miR-21 controls the apoptosis, invasion, and cellular growth involves the targeting of the PTEN gene, thus interfering with the Akt pathway and BCL-2 expression." (PMID 31766478, 2019). "In nasopharyngeal carcinoma, DEPDC1 knockdown downregulated various downstream targets, such as c−Myc, BCL2, MMP2 and MMP9, which participated in proliferation, tumorigenesis, and metastasis, suggesting that DEPDC1 might be a vital factor in these biological processes." (PMID 36768316, 2023). "In this study, we tested the sensitivity of two Nasopharyngeal Carcinoma (NPC) cell lines HK1 and C666-1 to Maritoclax, which is reported to repress anti-apoptotic protein MCL-1 and BH3 mimetic ABT-263, which selectively inhibits anti-apoptotic proteins BCL-2, BCL-XL and BCL-w." (PMID 33214852, 2020). "Interestingly, our results on Hone-1 nasopharyngeal carcinoma cells did not meet the unchanged Bcl-2 expression in M. charantia lectin-induced apoptosis in another nasopharyngeal carcinoma CNE-1 cells." (PMID 23091557, 2012).
synovial sarcoma (46 papers, 2003 to 2025). "The observed variation involved single genes whose overexpression has been associated with synovial sarcoma, including BCL2 and IGF2 as well as clusters of genes implicated in cell trafficking and differentiation." (PMID 19936258, 2009). "Bcl-2 is reported to be diffusely expressed in SFTs as well as in synovial sarcoma or in physiological stem cells and endocrine tissue." (PMID 41007078, 2025). "Synovial sarcomas (SSs) reveal diffuse expression of the apoptosis regulator BCL2 and often express a transmembrane glycoprotein CD99 (detected in >60% of the cases)." (PMID 41155410, 2025). "Other than these cytogenetic changes, another general constitutive alteration of synovial sarcomas is Bcl-2 expression, as assessed by immunohistochemistry." (PMID 39583501, 2024). "The open biopsy confirmed a spindle mesenchymal tumor with positive immunohistochemistry for CD99 (focal membrane staining), TLE-1 (nuclear staining), and BCL-2 (cytoplasmic staining), consistent with mediastinal synovial sarcoma." (PMID 39015801, 2024). "Immunohistochemical examination and CD99, TLE1, and BCL2 results were positive, so the diagnosis of synovial sarcoma was confirmed." (PMID 39015801, 2024). "The possibility of a monophasic synovial sarcoma of the oropharynx, considering the positivity for cytokeratins, CD99, and BCL2, or of its variant ossificans form, is discarded by the absence of an SYT translocation." (PMID 28050299, 2016). "A decrease in anti-apoptotic Bcl2 expression accompanied by an increase in pro-apoptotic Bax expression was observed in synovial sarcoma cells treated with UA for 6 and 9 h." (PMID 27219337, 2016). "Bcl-2 protein is regularly expressed in synovial sarcomas, and CD99, the product of the MIC2 gene, is seen in 67% of all cases." (PMID 23762651, 2013). "Immunohistochemically, the majority of synovial sarcomas express cytokeratins, epithelial membrane antigen, calponin, B-cell lymphoma 2 (BCL-2) and CD-99." (PMID 23148739, 2012). "The tumour showed positive staining with cytokeratin, epithelial membrane antigen, and Bcl-2 confirming the diagnosis of a biphasic synovial sarcoma." (PMID 22606585, 2011). "Although the present case showed strong bcl2 expression in the cytoplasm, however diagnosis of synovial sarcoma was deniable as the epithelial cells showed myoepithelial marker p63." (PMID 20509963, 2010). "Immunocytochemistry, i.e. cytokeratin and bcl-2 were advocated which showed positivity and final impression of synovial sarcoma was made." (PMID 21157548, 2010). "Other candidate was synovial sarcoma with both epithelial and mesenchymal lesion in the tumor expressing bcl-2." (PMID 20509963, 2010). "During immunohistochemical diagnosis the detection of markers such as keratin, epithelial membrane antigen (EMA) and Bcl2 are characteristic of synovial sarcoma." (PMID 12592363, 2003). "However, Bcl-2, CD99 and cytokeratin are characteristic markers commonly associated with synovial sarcomas." (PMID 41561516, 2025). "An explanation could be SW982 missing the pathognomonic SYT-SSX translocation which has been shown to directly regulate Bcl-2 expression among synovial sarcomas." (PMID 35887198, 2022). "Surprisingly, synovial sarcoma proved resistant to BCL-2 inhibitors in pre-clinical trials." (PMID 34065859, 2021). "Positive staining for CD99 and bcl-2 is also present in many cases of synovial sarcoma." (PMID 22741534, 2012). "Bcl-2 protein expression has been described as a characteristic marker of synovial sarcoma." (PMID 21157548, 2010). "bcl-2 positivity was restricted to spindle cells in biphasic and monophasic synovial sarcomas." (PMID 21157548, 2010). "Similarly, BCL2, one of the genes whose overexpression has even been suggested to constitute a molecular marker of synovial sarcoma, was induced in two batches of MSCs (batches 2 and 4) but not in the other two." (PMID 19936258, 2009).
synovial sarcoma (continued). "Therefore, antisense oligodeoxynucleotide targeted at BCL-2 (G3139) may serve as an appropriate therapeutic alternative for patients with BCL-2-positive synovial sarcomas." (PMID 39451213, 2024). "Additionally, the bcl-2 expression detected in synovial sarcoma could be explained by the characteristic translocation t (X, 18) that would affect the bcl-2 gene allocated in chromosome 18." (PMID 34200924, 2021). "In addition, upregulation of the PI3K/AKT/mTOR growth signaling pathway as well as increased expression of the pro-apoptotic protein BCL-2 (B-cell lymphoma-2) are hallmarks of synovial sarcoma biology, together eliciting a proliferative and apoptosis-resistant phenotype." (PMID 28056055, 2017). "Markers that are commonly expressed on synovial sarcoma cells include epithelial membrane antigen (EMA), BCL-2, and vimentin, while markers such as protein S-100, CD99, CD34, actin, and desmin are mostly negative." (PMID 40130143, 2025). "In contrast, synovial sarcoma exhibits a biphasic or monophasic spindle cell morphology with specific markers like TLE1, CD99, and Bcl-2, which aid in differentiation." (PMID 40578241, 2025). "Most synovial sarcomas show an immunoreaction for cytokeratin and epithelial membrane antigen (EMA) The positive rates for S‐100 protein, CD99, and Bcl2 are 30%, 60%–70%, and 75%–100%, respectively." (PMID 40964824, 2025). "Commonly utilized markers include Bcl-2, which exhibits substantial cytoplasmic positivity, and TLE1, which is very sensitive and specific for synovial sarcomas." (PMID 40718269, 2025). "Subsequently, the postoperative pathology reveals the presence of monophasic synovial sarcoma, specifically confirmed by positive expression of Vimentin, TLE1, and BCL-2 in immunohistochemical analysis." (PMID 39494240, 2024). "Bcl-2 is a relevant driver of synovial sarcoma (SS), being overexpressed in SS in TCGA data." (PMID 37834179, 2023). "We showed that co-targeting both BCL-2 and MCL-1 proves to be an effective therapeutic approach both in cell culture and animal models of synovial sarcoma, supporting translation into clinical trials." (PMID 34065859, 2021). "Synovial sarcomas are usually positive for vimentin, epithelial membrane antigen (EMA), bcl-2, CD99 (60–90%), and S-100 (30%)." (PMID 26101678, 2015). "The specimens of our patient were uniformly positive for Vimentin, BCL-2 and CD99 (markers which are typical for synovial sarcoma) and showed focal positivity for EMA." (PMID 24715974, 2014). "BCL2, a marker of anti-apoptotic signaling, is frequently positive in BCOR-CCNB3 sarcomas but is also seen in a wide range of other small round cell tumors, including synovial sarcoma and desmoplastic small round cell tumor (DSRCT)." (PMID 40932977, 2025). "Immunohistochemical markers like TLE1, BCL2, and CD56 are used to diagnose synovial sarcoma." (PMID 40747128, 2025). "Synovial sarcomas are negative for desmin, actin, S100 protein, and cytokeratin and positive for vimentin and Bcl-2." (PMID 37927755, 2023). "Our data suggest that among antiapoptotic Bcl-2 proteins, targeting Bcl-xL may break resistance to radiation in HNSCC, synovial sarcoma and NSCLC in vitro." (PMID 35887198, 2022). "Immunohistochemistry revealed the neoplastic cells expressing Vimentin, Mic-2, Bcl-2 and are negative for Myf-4, S-100, CK-7, CK-20, SMA, Desmin HMB-45, supporting diagnosis of poorly differentiated small cell variant synovial sarcoma." (PMID 23762651, 2013). "Synovial sarcoma are also positive for EMA, vimentin, BCL-2, CD99 and calponin." (PMID 16907985, 2006). "Even though co-treatment of radiation with Bcl-2 inhibition showed no relevant effect in our experiments across all entities, sole Bcl-2 inhibition interestingly induced measurable cell death within the synovial sarcoma cell lines Fuji and SYO-1 and not among SW982." (PMID 35887198, 2022).